IGFBP2 (insulin like growth factor binding protein 2)
Diseases named in the same sentence as IGFBP2 in open-access papers (continued):
Sharing a sentence is not in itself a finding about the gene and the disease.
melanoma (continued). "Overall, our results show that Igfbp2 plays a role in driving melanoma metastasis and growth in an age-specific manner and that neutralizing Igfbp2 levels in mice decreases tumor growth and lung colonization." (PMID 39007351, 2024). "In melanoma, IGFBP2 plays additional roles in the activation of the Epidermal Growth Factor Receptor (EGFR)-Signal Transducer adn Activator of Transcripton (STAT3) pathway, activating Programmed Death Ligand 1 (PDL1), and contributing to angiogenesis." (PMID 39007351, 2024). "To determine the contribution of IGFBP2 to this accumulation, we knocked-down IGFBP2 in aged fibroblasts, and then exposed melanoma cells to CM from the control and IGFBP2 knockdown fibroblasts." (PMID 39007351, 2024). "RPPA of the tumor lysates also confirmed increased Igfbp2 in melanoma tumors borne in aged mice, as well as an increase in fatty acid synthesis proteins, p-AKT, and the mTOR pathway." (PMID 39007351, 2024). "Neutralizing IGFBP2 in vitro reduces migration and invasion in melanoma cells, and in vivo studies demonstrate that neutralizing IGFBP2 in syngeneic aged mice reduces tumor growth and metastasis." (PMID 39007351, 2024). "This study reports that IGFBP2 secretion by aged fibroblasts induces lipid accumulation in melanoma cells, driving an increase in tumor invasiveness." (PMID 39007351, 2024). "We first examined the impact of Igfbp2 modulation on the growth of mCherry-tagged YUMM1.7 melanoma cells in vivo." (PMID 39007351, 2024). "Taken together with our previously published work, these data add a new dimension, showing that aged fibroblasts can drive melanoma cells to not only take up lipids but also synthesize de novo lipids through pathways driven by IGFBP2." (PMID 39007351, 2024). "Mechanistically, our studies suggest that increased IGFBP2 leads to elevated lipid synthesis by melanoma cells." (PMID 39007351, 2024). "The high expression of IGFBP2 is significantly correlated with the malignant progression and prognosis of melanoma and other tumors." (PMID 38099574, 2023). "IGFBP2 is believed to induce angiogenesis in melanoma by up-regulating the expression of pro-angiogenic VEGF-A, and subsequently triggering angiogenesis via interacting with integrin αVβ3 and activating the PI3K/AKT signaling cascade." (PMID 38124748, 2023). "IGFBP2 secreted in melanoma activates the PI3K/Akt pathway to promote tumor angiogenesis by binding to integrin αVβ3." (PMID 38099574, 2023). "IGFBP2 has been shown to promote PD-L1 expression by activating the EGFR-STAT3 signaling pathway in malignant melanoma." (PMID 38171932, 2023). "It was discovered that IGFBP2 controls PD-L1 expression in malignant melanoma by activating the EGFR-STAT3 signaling pathway." (PMID 37928523, 2023). "In malignant melanoma, IGFBP2 upregulates the PD-L1 expression and contributes to the immune evasion of cancer cells from host immunosurveillance." (PMID 36556226, 2022). "Ting Li have pointed out that IGFBP2 can regulate PD-L1 expression by activating EGFR-STAT3 signaling pathway in melanoma and participate in tumor immunotherapy resistance, but its specific mechanism needs to be further studied." (PMID 35493457, 2022). "In malignant melanoma, Insulin-like growth factor binding protein 2 (IGFBP2) regulates the expression of PD-L1 by activating the EGFR-STAT3 signaling pathway." (PMID 33732282, 2021). "We observed that IGFBP2 protein levels correlated with resistance to MAPKi in several BRAFV600-mutant melanoma cell lines, and is associated with poor prognosis in primary melanomas." (PMID 30143629, 2018). "Using matched melanoma samples derived from patients receiving dabrafenib + trametinib, we identify IGFBP2 as a potential biomarker for MAPKi resistance." (PMID 30143629, 2018). "Consistent with this, IGFBP2 protein levels correlate with resistance to MAPKi in several BRAFV600-mutant melanoma cell lines." (PMID 30143629, 2018).
melanoma (continued). "Through integrated transcriptomic, proteomic, and epigenomic analyses, we discover that SIRT6 haploinsufficiency increases IGFBP2 expression and promotes melanoma cell survival through the activation of IGF-1R/AKT signaling." (PMID 30143629, 2018). "The role of ADAMTS1 has been recently described in sarcoma and melanoma models, and the analysis of IGFBP2 proteolysis in EW7 and MUM2B cells (from sarcoma and melanoma, respectively) also showed similar patterns of proteolysis." (PMID 24962328, 2014). "It is up-regulated in a dose-dependent manner in melanoma cells treated with IGF-1, which indicates a possible role of IGFBP2 in the pathogenesis of melanoma." (PMID 24282616, 2013). "Since data in the human protein atlas indicated that older patients with melanoma with high IGFBP2 expression have lower probability of survival, we wanted to determine if IGFBP2 secreted from aged fibroblasts could have an impact on melanoma cells." (PMID 39007351, 2024). "Here, we report that in addition to elevated secretion of lipids capable of altering melanoma metabolism, aged stromal fibroblasts also secreted increased IGFBP2 levels that metabolically reprogram melanoma cells to synthesize lipid droplets that drive a pro-invasive/metastatic cell state." (PMID 39007351, 2024). "Finally, we examined the lungs of the aged mice treated with IgG or anti-Igfbp2 for metastasis using an anti-mCherry antibody to detect melanoma cells in the lung." (PMID 39007351, 2024). "To test whether IGFBP2 in an aged versus young environment played a role in melanoma cell invasion, we first performed 2D wound healing assays." (PMID 39007351, 2024). "We then performed a 3D spheroid assay, in which we embedded melanoma cell spheroids in collagen with young or aged fibroblasts, in which IGFBP2 was modulated, i.e., rIGFBP2 in young fibroblasts or neutralizing IGFBP2 antibody in aged fibroblasts." (PMID 39007351, 2024). "Melanoma cells co-cultured with aged dermal fibroblasts have higher levels of lipids relative to those co-cultured with young dermal fibroblasts, which can be lowered by silencing IGFBP2 expression in fibroblasts prior to treating with conditioned media." (PMID 39007351, 2024). "Neutralizing IGFBP2 decreases melanoma tumor growth and metastasis." (PMID 39007351, 2024). "IGFBP2 is considered an inducer of angiogenesis in melanoma." (PMID 38124748, 2023). "In addition, in malignant melanoma, IGFBP2 modulates PD-L1 levels via the mechanism of activating the EGFR-STAT3 signaling pathway." (PMID 35989938, 2022). "One study indicated that CD147 could induce malignant melanoma cell apoptosis through IGFBP2 and PTEN/PI3K/AKT signaling pathway." (PMID 35464411, 2022). "Highly expressed in our NTF2 low metastatic melanoma cells, IGFBP2 was downregulated upon NTF2 overexpression, suggesting these cells might show an improved drug response." (PMID 34880267, 2021). "Together, these data indicate that SIRT6 haploinsufficiency allows BRAFV600E melanoma cells to survive in the presence of MAPKi by increasing IGFBP2 expression, which in turn activates IGF-1R/IR and downstream AKT signaling, that can be blocked by IGF-1R/IR inhibition." (PMID 30143629, 2018). "Moreover, analysis of TCGA data for primary melanomas revealed that 20% display high SIRT6 mRNA, which anti-correlates with IGFBP2 (via RPPA), suggesting a repressive role of SIRT6 on IGFBP2 expression in melanoma." (PMID 30143629, 2018). "We overexpressed IGFBP2 in melanoma cells and observed increased p-AKT signaling and increased BODIPY staining in melanoma cells." (PMID 39007351, 2024). "Previous studies have found that IGFBP2 modulates the expression of PD-L1 through activating the EGFR-STAT3 signaling pathway, thereby exerting an anti-melanoma effect." (PMID 37088808, 2023). "SIRT6 can mediate the transcriptional regulation of IGFBP2 and therefore activate IGF-1R/AKT, which promotes the development of MAPK inhibitor resistance in melanoma." (PMID 35915188, 2022).
melanoma (continued). "By integration of RNA‐seq and RPPA analysis, we found that PAR, IGFBP2, Connexin 43, and SOD2 were similarly altered in both assays, emphasizing their significance in the regulatory role of ALDOC of melanoma malignancy." (PMID 33274599, 2021). "In melanoma, syntenin induces angiogenesis by activating Akt, leading to the expression of HIF-1α and the transcription of IGF-binding protein-2 (IGFBP-2), which induces the production of VEGF in endothelial cells and angiogenesis." (PMID 32106836, 2020). "Here, through an unbiased screening approach, we identified SIRT6-mediated transcriptional regulation of IGFBP2, and consequent activation of IGF-1R/AKT, to play a role in melanoma MAPKi resistance." (PMID 30143629, 2018). "For melanoma, the levels of MAPK_pT202_Y204, PTEN, and Bcl-2 are decreased, and IGFBP2, E-Cadherin, Akt_pT308, and Akt_pS473 are increased." (PMID 30442178, 2018). "In our study, we first found that up-regulation of IGFBP5 decreased HIF1α expression and the other IGFBPs family members, IGFBP2, IGFBP4, IGFBP6, and IGFBP7 to some extent in melanoma cells." (PMID 26010068, 2015). "Pearson correlation coefficient analysis was used to examine the relationship between mRNA and protein expression of ANXA1, CAV-1, CAV-2, EphA2, IGFBP2 and PTRF in the panel of melanoma cell lines." (PMID 25594008, 2014). "There does not appear to be to be an increase in the transcription of IGFBP2, suggesting that IGFBP2 is taken up by melanoma cells rather than induced." (PMID 39007351, 2024). "To confirm these findings, we performed IGFBP2 immunohistochemistry (IHC) on treatment-naive tumor biopsies from 34 melanoma patients (21 BRAFV600E/K and 13 non-BRAF mutant tissues)." (PMID 30143629, 2018). "To evaluate whether SIRT6 and IGFBP2 levels anti-correlate in human melanoma tissues, we performed SIRT6 IHC on 21 BRAFV600E/K melanomas stained for IGFBP2, and observed a statistically significant inverse correlation (Spearman’s r = −0.462; P = 0.035)." (PMID 30143629, 2018). "IGFBP-2, IGFBP-3 and IGFBP-7 expression was elevated in epithelial-like melanoma cells." (PMID 25940796, 2015). "Furthermore, high levels of IGFBP2 correlate with resistance to Mitogen Activated Protein Kinase (MAPK) inhibitors and may represent a marker for therapy resistance in melanoma." (PMID 39007351, 2024). "Additionally, elevating the IGFBP2 expression could lead to attenuate sensitivity to MAPK signaling inhibitors, and thereby increasing BRAFV600E melanoma cell survival via triggering IGF-1R/AKT signaling pathway." (PMID 33768092, 2021). "Employing CRISPRCas9 screen targeting chromatin regulators illuminate that SIRT6 haploinsufficiency could upregulate IGFBP2 expression level as well as attenuate sensitivity to MAPKi, and thereby enhancing BRAFV600E melanoma cell survival via triggering IGF-1R/AKT signaling pathway." (PMID 33768092, 2021). "CD271 knockdown was found to eliminate the capacity of melanoma cells to form heterogeneous tumors most likely through the downregulation of mediators for melanoma invasion and metastasis (GLI-2, SOX2 and ERBB3), angiogenesis (IGFBP-2), proliferation (FST and MITF) or chemoresistance (RHOJ)." (PMID 25351876, 2015). "We found that expression of ANXA1, CAV-1, CAV- 2, EphA2, IGFBP2 and PTRF mRNA did not correlate with response to dasatinib in the panel of 8 melanoma cell lines." (PMID 25594008, 2014).
Insulin resistance (40 papers, 2013 to 2026). Increased resistance towards insulin, that is, diminished effectiveness of insulin in reducing blood glucose levels. "In mice and humans, low plasma levels of IGFBP-2 are associated with higher body weight, adiposity, insulin resistance, and the development of NAFLD." (PMID 37854178, 2023). "In population-based studies IGFBP2 levels correlate inversely with insulin resistance, metabolic syndrome and type 2 diabetes risk." (PMID 34835949, 2021). "However, many unsolved issues still hinder the role of IGFBP2 in insulin sensitivity and insulin resistance, and the suggested the association with type 2 diabetes, which we discuss below." (PMID 33498859, 2021). "IGFBP2 was an independent predictor of insulin sensitivity, which suggests that IGFBP2 plays a central role in the insulin/IGFs system crosstalk and it is closely linked to insulin resistance." (PMID 33498859, 2021). "Among the downregulated genes, Ppp1r3g, which has a role in controlling glycogen synthesis, and Igfbp2, which functions in insulin resistance, were markedly reduced." (PMID 38619504, 2024). "Among the prognostic marker candidates, SHBG and IGFBP2 tightly correlated with insulin resistance, while others displayed a weaker correlation." (PMID 39589852, 2024). "Parallel to the observation with miR-130b, downregulation miR-873 in a rat model of gestational diabetes was reported to reduce insulin resistance and myocardial injury by upregulating IGFBP-2, allowing promotion of PI3K/AKT/mTOR signaling." (PMID 35597813, 2022). "In a murine model of non-alcoholic fatty liver disease, downregulation of miR-130b-5p, which targets IGFBP-2, prevented lipid accumulation and insulin resistance by increasing IGFBP-2 and AKT activation." (PMID 35597813, 2022). "As regarding to insulin sensitivity and insulin resistance, the proposed mechanism by which IGFBP2 improves insulin sensitivity, is through IGFs/IGFBP2-dependent and independent model." (PMID 33498859, 2021). "In this line, our group (2017) found that both mRNA and IGFBP2 protein in visceral adipose tissue were decreased in 13 morbid obese patients with high insulin resistance when compared with in 12 morbid obese patients with low insulin resistance." (PMID 33498859, 2021). "Prior studies involving transgenic mice overexpressing human IGFBP2 showed that the mice resisted diet-induced weight gain and insulin resistance." (PMID 31597091, 2019). "Studies in humans and in experimental animal models have shown that IGFBP-2 is a key factor in the insulin-IGF cross-talk and also linked to insulin resistance." (PMID 24725803, 2014). "It is speculated that the rise in IGFBP-2 during CI reflects a compensatory response to the catabolic state induced by the illness, which is characterized by muscle wasting, insulin resistance, and disrupted glucose metabolism." (PMID 39585162, 2024). "IGFBP2 has emerged as an important mediator of insulin resistance and metabolic health." (PMID 36586437, 2023). "Moreover, Igfbp2, an emerging target for insulin resistance and liver steatosis, was increased with FGFR4 KD." (PMID 36586437, 2023). "Additionally, IGFBP2 was presented as a biomarker of insulin sensitivity and reduced levels of circulating IGFBP2 correlated with insulin resistance." (PMID 34646401, 2021). "In addition, subjects with impaired glucose tolerance showed more pronounced insulin resistance and lower serum IGFBP2 levels in comparison with healthy control." (PMID 33498859, 2021). "Moreover, Igfbp2 has been shown to protect from the development of insulin resistance in a model of diet-induced obesity and its activity is modulated by the anti-diabetic drug Metformin41." (PMID 32737396, 2020). "Interestingly, these studies suggest an age-related increase in plasma IGFBP-2 levels, particularly in individuals over 50, which parallels the development of insulin resistance and may serve as a mortality predictor after adjusting for insulin sensitivity." (PMID 39585162, 2024).
Insulin resistance (continued). "The role of IGFBP2 in type 2 diabetes may be related with regulation of IGFs, glucose uptake, and PI3K/Akt pathway, which indicates that IGFBP2 may have a specific role in the pathway of insulin resistance, either by dependent- or independent-IGF signaling pathway." (PMID 33498859, 2021). "Given the established links between insulin resistance and the development of NAFLD, it is possible that IGFBP-2 contributes indirectly to a low LF phenotype by enhancing insulin sensitivity despite the presence of visceral obesity." (PMID 37854178, 2023). "Insulin-like growth factor binding protein-2 (IGFBP-2) correlates negatively with body weight and insulin resistance." (PMID 36145221, 2022). "Our data indicate regulation of IGFBP2 to be more dependent on the lipid status of the liver, as shown in the aP2-SREBP-1c mice with systemic insulin resistance and aggravated fatty liver." (PMID 32532003, 2020). "Further studies on these rats may help link CYP7B1 to precocious changes in the development of insulin resistance, particularly regarding hepatic secretion of TG-enriched VLDL and IGFBP2 levels via oxysterols." (PMID 41465421, 2025). "Insulin resistance stimulates the hepatic synthesis of insulin-growth factor 1 (IGF-1) and increases its bioactivity by reducing insulin-growth factor binding protein 1 (IGFBP-1) and 2 (IGFBP-2) levels." (PMID 39199391, 2024). "In our study, IGFBP2 showed no changes in its serum concentration in terms of specific hepatic insulin resistance, but a significant reduction in serum was related to aggravate liver fat when whole-body insulin resistance is present." (PMID 32532003, 2020). "In fact, this activation was dependent to insulin resistance grade, since the HIR-MO individuals showed less staining than LIR-MO subjects, suggesting that HIR-MO subjects have less activity of PPAR-γ–RXR-α, and further, less activity of IGFBP-2." (PMID 31547433, 2019). "IGFBP2 has also been demonstrated to activate the AMP-activated protein kinase (AMPK) signaling pathway, resulting in intracellular translocation of glucose transporter 4 (GLUT4), stimulating glucose uptake, improving insulin resistance, and subsequently impacting lipid deposition in hepatocytes." (PMID 40608848, 2025). "In addition, low IGFBP-1 and IGFBP-2 coupled with elevated IGF-1, may represent compensatory mechanisms in response to increasing insulin resistance." (PMID 29351335, 2018).